KRAS (KRas proto-oncogene, GTPase)
Diseases named in the same sentence as KRAS in open-access papers (continued):
Sharing a sentence is not in itself a finding about the gene and the disease.
colorectal cancer (continued). "For example, high-dose vitamin C exhibits anticancer effect in KRAS- and BRAF-mutant colorectal cancer (CRC) cells by promoting ROS accumulation, inducing the S-glutathionylation of GAPDH at Cys152, and inhibiting glycolysis." (PMID 40227215, 2025). "Among the five samples of colorectal cancer (CRC) analyzed, three exhibited alterations in the KRAS gene: CRC3 contained a substitution for G12D, CRC5 showed a G12S mutation, and CRC4 carried a Q61H variant." (PMID 41009816, 2025). "KRAS wild-type colorectal tumors are usually sensitive to EGFR blockade, e.g., cetuximab and panitumumab are one of the mainstays of targeted therapy for colorectal cancer, but resistance almost always develops within a few months of initiating therapy." (PMID 40438683, 2025). "Previous studies have indicated that the concomitant use of EGFR inhibitors and KRAS inhibitors can yield clinical benefits in the treatment of non-small cell lung cancer (NSCLC) and colorectal cancer." (PMID 40689200, 2025). "Typical of MMR-proficient colorectal adenocarcinomas (and adenomas) in general, APC was mutant in all tumors but one (colorectal carcinoma of individual III.6 from HNPCC20), and KRAS, too, was frequently affected." (PMID 41023686, 2025). "KRAS is among the most frequently mutated genes in cancer patients, with oncogenic mutations found in ~ 30% of lung adenocarcinomas (LUAD), ~ 95% of pancreatic ductal adenocarcinomas (PDAC), and ~ 45% of colorectal carcinomas (CRC)." (PMID 39592415, 2025). "In people with and without disabilities, EGFR gene tests related to lung cancer and KRAS and NRAS gene tests related to colorectal cancer appeared as the top genetic test items among people aged ≥40 years." (PMID 38711356, 2024). "In this context, we investigated circulating tumor DNA (ctDNA)/KRAS in conjunction with HPV and EBV infections in gastric and colorectal cancer." (PMID 39673361, 2024). "Another long peptide pooled mutant-KRAS vaccine is being investigated in a phase I trial in combination with nivolumab and ipilimumab in patients with resected MMR-proficient colorectal cancer and pancreatic cancer (NCT04117087)." (PMID 38576709, 2024). "The drug carbamazepine, an autophagy inducer, was used on colorectal cancer cell lines, HCT1116 and Hke3 (KRAS mutant and wildtype)." (PMID 38446332, 2024). "Oncogenic KRAS and KRAS G13D carrying CD133+ microvesicles derived from colorectal cancer were proven to promote chemotherapy resistance." (PMID 38609981, 2024). "There are even conclusions that FURIN is a driver of pro-oncogenes in KRAS and BRAF mutant colorectal cancer." (PMID 39350850, 2024). "In colorectal cancer, ESMO suggests that an optimal gene panel should detect KRAS, NRAS, BRAF, NTRK, and ERBB2 amplification, although NGS is still only considered for research purposes." (PMID 38213074, 2024). "While usually SMAD4 loss alone does not initiate tumor formation, it promotes progression after cancer is initiated by other oncogenes like KRAS in PDAC and APC in colorectal cancer." (PMID 38666907, 2024). "This study performed Ras pull-down assays using the KRAS wild-type colorectal cancer cell line HT29 and KRAS mutant colorectal cancer cell lines SW837G12C, LS180G12D, SW480G12V, and HCT116G13D." (PMID 38216883, 2024). "cg09317508 is positioned near the Nephrocytin 4 gene (NPHP4), a WNT pathway gene and is upstream of microRNA MIR4689, which has been reported to interact with KRAS and AKT in colorectal cancer." (PMID 38554236, 2024). "The KRAS and BRAF status holds pivotal significance in tailoring treatment strategies and predicting the prognosis of colorectal cancer (CRC)." (PMID 39220126, 2024). "This could be due to the absence of PIK3CA mutation in half of colorectal cancer patients, and the frequent co-occurrence of KRAS pathogenic variants with PIK3CA mutations, leading to a shorter reported PFS and potentially reduced activity against PIK3CA inhibitors." (PMID 39070139, 2024).
colorectal cancer (continued). "Kirsten Rat Sarcoma Viral Oncogene Homolog (KRAS) is a significant driver in several cancers, including non-small cell lung cancer (NSCLC), colorectal cancer (CRC), and pancreatic duodenal adenocarcinoma (PDAC)." (PMID 39001451, 2024). "Among 1347 colorectal carcinoma cases with KRAS mutation data in the two United States‐wide prospective cohort studies, we detected KRAS c.34G>T (p.G12C) mutation in 43 cases (3.2%) and other KRAS mutations (i.e., KRAS mutations that were not c.34G>T) in 467 cases (35%)." (PMID 39039804, 2024). "It must be noted that this is an acute increase in KRAS expression, which might have very different effects than KRAS overexpression caused by gene amplification that has been associated with resistance to EGFR and KRAS targeted therapies in colorectal cancer cell lines." (PMID 37627169, 2023). "Therefore PDEδ inhibitors might become a novel target for KRAS mutant colorectal cancer." (PMID 37777749, 2023). "Shi-r used a deep artificial neural network to predict the gene status of KRAS, NRAS, and BRAF in patients with liver metastasis of colorectal cancer." (PMID 38201314, 2023). "evaluate deep-learning-based prediction for MSI, BRAF, KRAS, NRAS, and PIK3CA biomarker status in colorectal cancer from histopathology slides." (PMID 36958327, 2023). "We assessed the clinicopathological features and prognostic values of KRAS, NRAS, BRAF, and DNA mismatch repair status in colorectal cancer (CRC) to provide real-world data in developing countries." (PMID 36862900, 2023). "Bi-3406 also synergizes with MEKi to induce significant tumor regression in KRAS-mutant cell line xenografts of pancreatic and colorectal cancer and of PDX models of colorectal cancer." (PMID 37190303, 2023). "Among the three isoforms (KRAS, NRAS, and HRAS), Kirsten rat sarcoma viral oncogene homolog (KRAS) is the common oncogene in a large percentage of cancers, including pancreatic cancer, non-small cell lung cancer (NSCLC), and colorectal cancer." (PMID 37662925, 2023). "Accumulating pieces of evidence report that the KRAS G12C inhibitors such as Sotorasib (AMG 510), ARS-1620, and Adagrasib (MRTX849) are becoming resistant in non-small-cell-lung-cancer (NSCLC) and colorectal-cancer (CRC) patients." (PMID 36975507, 2023). "Importantly, lower mutation rates in two FDA‐approved therapeutic targets, namely, EGFR in lung cancer and KRAS in colorectal cancer, were identified, indicating that young patients with lung cancer or colorectal cancer may have a smaller chance of benefitting from targeted therapies." (PMID 37610374, 2023). "The effect of SJ-C1044 on oncogenic KRAS-mediated MEK and ERK phosphorylation was investigated in LS513, a KRAS(G12D)-mutant colorectal cancer cell line." (PMID 37504287, 2023). "Studies with KRAS inhibitors mirror earlier work, which demonstrated the ability of BRAF and MEK inhibitors to enhance the therapeutic activity of ICB in LUAD, colorectal cancer, and melanoma mouse models." (PMID 37581538, 2023). "The suppressive role of miRNA-487b was also indicated in colorectal cancer via targeting MYC, SUZ12 and KRAS." (PMID 37108073, 2023). "Sotorasib received orphan drug designation from the US FDA in June 2019 for KRAS p.G12C-positive non-small cell lung cancer (NSCLC) and colorectal cancer." (PMID 37509241, 2023). "Oncogenic KRAS has also been shown to repress tumor-intrinsic IFN signaling in lung cancer, colorectal cancer, and pancreatic cancer." (PMID 37581538, 2023).
colorectal cancer (continued). "To test its potency against KRAS and BRAF mutant colorectal cancer cells, we treated three KRAS-mutant cancer cell lines (HCT116, LS513, and SW620) or a BRAF-mutant cancer cell line (HT29) with SJ-C1044 in a cell growth assay." (PMID 37504287, 2023). "Based on TCGA data, there was a positive correlation between CCL28 and KRAS expressions in PDAC and colorectal carcinomas." (PMID 37380804, 2023). "Based on TCGA data, there was a positive correlation between FOSL2 and KRAS expression in PDAC, colorectal carcinomas, and lung adenocarcinomas." (PMID 37380804, 2023). "Combination strategies of KRAS inhibition with immunotherapy in treating advanced or recurrent colorectal carcinoma (CRC) may need to be assessed in circulating tumour cells (CTCs) to achieve better clinical outcomes." (PMID 37761948, 2023). "In an analysis of 38 patients with KRAS G12C cancers treated with adagrasib monotherapy, including 27 with NSCLC and 10 with colorectal cancer, mechanisms of acquired resistance were identified in 45%." (PMID 36284306, 2022). "To explore the potential vulnerability of KRAS-Mut subtypes in CRC, we compared the gene dependencies based on large-scale RNAi screening among the colorectal cancer cell lines in the Cancer Dependency Map (DepMap) dataset." (PMID 35836817, 2022). "IHC staining of tissue microarrays of lung and colorectal cancer patient tissues showed that 63% of lung cancer (n = 69/108) and 62% of colon cancer (n = 31/50) expressed high levels of DX2 and KRAS proteins." (PMID 35546148, 2022). "To this end, we have previously obtained a stable complex comprised of the internalizing anti-EGFR-antibody cetuximab bound to cationic protamine and the anionic siRNA against KRAS and PIK3CA that specifically enters colorectal cancer cells." (PMID 36457063, 2022). "In colorectal cancer (CRC), KRAS mutant tumor cells increased glycolysis and glutamine utilization resulting in cell death upon inhibition of glyceraldehyde 3-phosphate dehydrogenase (GAPDH)." (PMID 36048281, 2022). "In an interesting study performed on colorectal cancer (CRC) cells, KRAS gene editing was effectively performed by designing a suitable sgRNA, using the CRISPR/Cas9 system, and using nanotechnology for efficient delivery of the CRISPR/Cas9 system." (PMID 35715750, 2022). "Other targeted treatments addressing small defined sub-sets of colorectal cancers include NTRK inhibitors for colorectal cancers with NTRK fusions and specific KRAS G12C inhibitors for cancers with this KRAS substitution." (PMID 36295658, 2022). "Second, vitamin C selectively kills KRAS and BRAF mutant colorectal cancer cells by targeting glyceraldehyde 3-phosphate dehydrogenase." (PMID 35956413, 2022).
colorectal cancer (continued). "Previous research shows the PLCD1 expression is downregulated in colorectal cancer cells, leading to induce E-cadherin expression, and PLCD1 overexpression reduced the malignant progression via E-cadherin and KRAS/MEK/ERK signal attenuation." (PMID 35836489, 2022). "More than 80% of mutations in KRAS occur at codon 12, found prevalently as G12D substitution in 70% of pancreatic ductal adenocarcinoma (PDAC) and in almost 50% of colorectal carcinoma (CRC) cases." (PMID 35014625, 2022). "In addition to promoting metastasis, the DDX3X-induced YAP1/SIX2 axis might be responsible for resistance to treatment with the anti-EGFR antibody cetuximab (CTX) in colorectal cancer harbouring wild-type KRAS via enhanced autophagy and anti-apoptotic mechanisms." (PMID 33627125, 2021). "In colorectal cancer harbouring mutant KRAS, DDX3X-induced expression of KRAS activates the RAF/MEK/ERK/c-Jun pathway to suppress the tumour suppressor gene PTEN, a negative regulator of the PI3K/AKT pathway." (PMID 33627125, 2021). "Consistently, LY3214996 exhibited a well-tolerable and synergistic activity profile in xenograft models of KRAS-mutant NSCLC and colorectal cancer in combined modality settings." (PMID 34946644, 2021). "Colorectal cancer cells can transfer mutant KRAS to neutrophils through exosomes, thereby promoting NET formation by mediating upregulation of IL-8, ultimately leading to colorectal cancer deterioration." (PMID 34204148, 2021). "InventisBio has developed a KRAS G12C inhibitor (D-1553), which has been positioned in NSCLC and colorectal cancer." (PMID 34845311, 2021). "Other clinical studies evaluating similar combinations in RAS-mutant colorectal cancer (NCT03981614), KRAS-mutant NSCLC (NCT03170206), and in children and young adults with brain tumors (NCT03434262) are ongoing." (PMID 33456709, 2021). "Genes upregulated in KRAS‐mt tumors included HOXB6 and HOXB8, two homeobox genes that have been previously reported to be dysregulated in colorectal cancer." (PMID 33817986, 2021). "In this study, KRAS status was collected only in patients with NSCLC and colorectal cancer, statistical significance was found in patients with colorectal cancer." (PMID 34239621, 2021). "We also compared isogenic human colorectal cancer cells with intact (DLD1, DKO1) or disrupted (DKS8) KRAS oncogene." (PMID 34136107, 2021). "Mutant KRAS, the principal isoform of RAS, plays a pivotal role in the oncogenesis of colorectal cancer by constitutively activating the RAF/MEK/ERK and PI3K/AKT pathways." (PMID 34347396, 2021). "This comprehensive integrative -omics analysis confirms known and adds novel genes, proteins and metabolic pathways regulated by mutant KRAS and BRAF signaling in colorectal cancer." (PMID 34233735, 2021). "The Kirsten rat sarcoma viral oncogene homolog or KRAS gene is aberrant in NSCLC (up to 25% of cases), colorectal cancers, and pancreatic ductal adenocarcinomas." (PMID 35008185, 2021).
colorectal cancer (continued). "The present study attempts to explore the inhibitory impact of KA25 and KA39 derivatives on Akt1 and Akt2 phosphorylation in three colorectal cancer cell lines (HT-29, LoVo, and SW403) with specific PIK3CA and KRAS statuses." (PMID 33916378, 2021). "Based on our data, planning for a clinical trial is underway: it will examine the combination treatment of KRAS G12C inhibitors and IN10018 for KRAS G12C mutant colorectal cancers soon." (PMID 34151545, 2021). "In colorectal cancer, DDX3X increases the expression of KRAS by promoting SP1 binding to the KRAS promoter to facilitate tumour metastasis." (PMID 33627125, 2021). "The determination of molecular markers (KRAS and BRAF oncogenes) has been used to stratify cases of colorectal cancer, and the choice of treatment and advances in targeted therapy have yielded significant increases in patient survival." (PMID 33183271, 2020). "Analysis of KRAS, BRAF and PI3KCA genes helps in the prognosis as well as in the treatment of colorectal cancer." (PMID 32000721, 2020). "In colorectal cancers, the most frequent mechanism of cetuximab resistance has been reported as genomic alterations in downstream effectors of EGFR such as KRAS, NRAS, BRAF, and PIK3CA." (PMID 32698317, 2020). "sEVs derived from colorectal cancer (CRC) mutant KRAS-expressing cells contain proteins and enzymes involved in metabolism and glycolysis and can enhance the growth of wild type KRAS cells." (PMID 32015297, 2020). "Previous studies have also shown high concordance for blood and tissue alterations, such as those in the KRAS, NRAS, APC, and BRAF genes, in colorectal cancer." (PMID 32187847, 2020). "Sidedness is a surrogate of a wide spectrum of colorectal cancer (CRC) biology features (embryology, microbiome, methylation, microsatellite instability (MSI), BRAF, aging, KRAS, consensus molecular subtypes (CMS), etc.), which result in prognostic factors." (PMID 32545884, 2020). "Colorectal cancer (CRC) is a heterogeneous disease with a complex biology and a wide number of altered genes such as BRAF, KRAS and PIK3CA." (PMID 32066410, 2020). "Detection of some genes such as c-MYC, KRAS, BRAF, PIK3CA, PTEN can be used as a predictor of colorectal cancer." (PMID 33014884, 2020). "It has also been demonstrated that KRAS-IRF 2 axis drives immunosuppression and immunotherapy resistance of colorectal cancer." (PMID 33245101, 2020). "RAS proteins (KRAS, NRAS and HRAS) are frequently activated in different cancer types (e.g., non-small cell lung cancer, colorectal cancer, melanoma and bladder cancer)." (PMID 33187149, 2020). "Systemic review and meta-analysis will be performed to summarize the accuracy of KRAS mutation measurement in colorectal cancer using liquid biopsy sample, and subgroup analysis will be performed on different testing platforms, and on metastatic and non-metastatic colorectal cancer." (PMID 32590745, 2020). "KRAS, which was involved in NCCN guidelines for colorectal cancer in 2008 for the first time, has proven to be a key biomarker in applying EGFR-targeted therapies." (PMID 33628729, 2020). "In addition, patients that regularly use NSAIDs may reduce their risk of certain subtypes (i.e., those with no BRAF/KRAS gene mutation) of colorectal cancer (CRC)." (PMID 32722165, 2020). "In the well-studied example of colorectal cancer, monotherapy targeting the epidermal growth factor receptor (EGFR) inevitably resulted in the expansion of KRAS mutant subpopulations that drive patient relapse." (PMID 32898185, 2020).